CAV1 (caveolin 1)
Diseases named in the same sentence as CAV1 in open-access papers (continued):
Sharing a sentence is not in itself a finding about the gene and the disease.
infection (continued). "Caveolin-1 knockdown and caveolae disruption via plasmalemmal cholesterol depletion pronouncedly reduce infection by both microorganisms." (PMID 39324816, 2024). "In the brains of mice infected with A. cantonensis, there was a significant increase in Cav-1 levels, p-Cav-1 levels, and p-Cav-1/Cav-1 ratios on day 10 after infection, with a subsequent increase observed as infection progressed." (PMID 38922036, 2024). "All the mice, except one Cav1-/- mouse, recovered from infection triggered with 5 × 106 CFU of bacteria/mouse (CFU/m), while all mice died 24 hr after intravenous injection of 5 × 108 CFU/m." (PMID 38517935, 2024). "Three hours after infection, many bacteria were found in the cells, and the co-localization of P. gingivalis/gingipain and Cav-1 was also detected with further increasing Cav-1 expression on the cell membrane surfaces." (PMID 36631446, 2023). "Genistein, an FDA-approved pharmacological inhibitor of Src kinase-dependent phosphorylation of caveolin-1, decreased infection in mink." (PMID 38033586, 2023). "Next, plasmids expressing WT and DN caveolin-1 were transfected into ST cells, followed by infection with PDCoV." (PMID 37962380, 2023). "We present here that HAdV26 infection of human epithelial cells with high expression of αvβ3 integrin, one of the putative HAdV26 receptors, is caveolin-1- and partially dynamin-2-dependent." (PMID 35924932, 2022). "To study role of caveolin-1 in HAdV26 infection pathway we decreased its expression by transfection with specific siRNA prior infection with HAdV26." (PMID 35924932, 2022). "In our cell model, downregulation of clathrin increased infection with HAdV5, while downregulation of caveolin-1 decreased infection with HAdV5." (PMID 35924932, 2022). "The data suggest that powerful invasive L. interrogans transmigrate through vessel wall maintained high viability and the ITGB1 and CAV-1 mediate the transcytosis of the spirochete during infection." (PMID 36137081, 2022). "HAdV26 infection in the A549 cell clone with increased expression of αvβ3 integrin is caveolin-1-dependent." (PMID 35924932, 2022). "Here we examined the role of dynamin-2, clathrin, and caveolin-1 in HAdV26 infection and we showed that HAdV26 infection of A549 cell line involves dynamin-2 and clathrin but is caveolin-1-independent." (PMID 35924932, 2022). "Here we have shown that in the settings where HAdV26 can use αvβ3 integrin as a receptor, presence of caveolin-1 is needed for successful infection." (PMID 35924932, 2022). "Role of caveolin-1 in HAdV26 cell infection was additionally assessed in cell clones with stably downregulated caveolin-1." (PMID 35924932, 2022). "The data suggest that the ITGB1 in THP-1 and both the ITGB1 and CAV-1 in HUVEC mediate the internalization of the spirochete during infection." (PMID 36137081, 2022). "HAdV26 infection in A549 cell line expressing low amount of αvβ3 integrin is caveolin-1-independent." (PMID 35924932, 2022). "Exposure of pericytes to HIV-1 significantly decreased occludin levels 48 h after infection, followed by significant increases in caveolin-1 and alix expression which steadily climbed to both 48 and 72 h after infection." (PMID 36476484, 2022). "We observed a similar phenotype when the infection foci contained caveolin-1- or epsin-1-depleted cells." (PMID 34781738, 2021). "Studies further upstream indicated that viral entry into keratocytes was dependent on cell membrane lipid rafts and caveolin-1 within minutes of infection." (PMID 34960773, 2021). "We found that the TG group exhibited earlier phosphorylation of Src and CAV1 following infection, and the levels of phosphorylated Src and CAV1 in the TG group were higher than those in the WT group at the same time points post-infection." (PMID 33966642, 2021). "It is evident when overexpression of caveolin-1 resulted in a clear increase in the infection efficiency compared to the control cells." (PMID 33761945, 2021).
infection (continued). "Similar approaches have also been utilized to demonstrate the redundant role of Cav1 during infection utilizing global Cav1 mutant mice as well as the requirement for Notch expression on basophils and CXCR5 expression on CD11c+ cells in T. muris expulsion." (PMID 33952360, 2021). "After 4 d of infection with the caveolin-1 siRNA-LV, caveolin-1 mRNA and protein levels were knocked down by 90% and 100%, respectively." (PMID 32676485, 2020). "In this review, the multifunctional roles of caveolae, particularly CAV-1, in different infection stages, as well as related signaling pathways, will be comprehensively summarized and discussed." (PMID 32357558, 2020). "Studies on human immunodeficiency virus (HIV) revealed multiple ways in which CAV-1 participates in signaling regulation during infection." (PMID 32357558, 2020). "To validate the role of caveolin-1 in early alphavirus neuroinvasion in vivo, we infected WT and Cav-1−/− mice with either VEEV (10 PFU) or WEEV (1000 PFU) via f.p. infection and examined peripheral and CNS viral burdens at 1 and 3 dpi." (PMID 32047126, 2020). "Cav-1-deficient mice exhibit diminished CNS VEEV and WEEV titers during early infection, whereas viral burdens in peripheral tissues remained unchanged." (PMID 32047126, 2020). "Consistent with this, Cav-1 deficiency reduced alphavirus transcytosis in vitro and led to reduced titers of VEEV or WEEV in the CNS during early infection in vivo." (PMID 32047126, 2020). "Gonococci use Cav-1 phosphorylation and downstream signaling to switch from local to invasive infection." (PMID 33195223, 2020). "Previous works have indicated that caveolae and CAV-1 play significant roles in every step of the viral life cycle with the focus on entry, and consequently is essential for productive infection." (PMID 32357558, 2020). "HBV has been shown to follow a caveolin-1-mediated entry pathway to initiate productive infection in HepaRG cells." (PMID 32570893, 2020). "To confer the role of caveolae during RABV endocytic, we performed caveolin-1(Cav1) knockdown to assess the infection of RABV." (PMID 31196105, 2019). "In L929 fibroblasts caveolae or Cav-1 mediated processes were dispensable for the establishment of productive infections with strains 22L and Chandler/RML." (PMID 30970585, 2019). "The mortality rate is a 100% for the wild-type mice while only half of Cav-1−/− mice die after 48 h, and the survivors recover from the infection." (PMID 29250058, 2017). "A recent study indicates CAV1-mediated endocytosis is advantageous for productive CSFV Shimen infection in macrophages." (PMID 28915564, 2017). "This systematic approach revealed that CD81, CD44, CD98, caveolin-1 and catenin delta-1 were down-regulated during infection whereas GRP-78 was up-regulated." (PMID 29121670, 2017). "Infection is accompanied by neutrophil recruitment in both Cav-1−/− and wild-type, but isolated neutrophils of Cav-1−/− mice are less efficient in phagocytosis." (PMID 29250058, 2017). "It is concluded that CAV-1 is endemic in free-ranging red foxes in the UK and that many foxes have inapparent infections in a range of tissues." (PMID 27796367, 2016). "This study has shown that 18.8% of red foxes from across the UK, all of which were free from gross evidence of ICH on post-mortem examination, were positive for CAV-1 sequences by PCR, consistent with inapparent infection." (PMID 27796367, 2016). "In view of the low viral loads in some tissues, a highly sensitive molecular assay, such as nested PCR, is necessary to estimate the true prevalence of inapparent infections with CAV-1." (PMID 27796367, 2016). "OMVs from non‐typeable Haemophilus influenzae were shown to enter and colocalize with caveolin 1 (Cav‐1), a marker of caveolae, by western blotting of epithelial cell lysates after infection." (PMID 27529760, 2016).
infection (continued). "In a variety of human cell lines, caveolin-2 forms a heterodimer with caveolin-1, which after infection with P. aeruginosa, co-localizes with CFTR and P. aeruginosa." (PMID 26047157, 2015). "To identify caveolin-1-positive compartments where MPyV virions appear in the absence of microtubules, we processed nocodazole-treated cells later (5 h) post-infection for immunogold labeling of caveolin-1 on thawed cryosections of the cells." (PMID 24810588, 2014). "Instead, Src kinase was phosphorylated on specific tyrosine residues upon infection with H. pylori G27 independently of Cav1." (PMID 23592983, 2013). "Src kinase activity was also increased in caveolin-1 rich endosomal fractions after infection, and Src phosphorylation and CXCL1 induction were both decreased in caveolin-1-/- mice corneas compared to wild type mice." (PMID 24147000, 2013). "MKN45 cells were transfected with a luciferase reporter plasmid pGL3 containing the human proximal Cav1 promoter (pGL3-CAV1p) followed by a 16 h infection with CagA-proficient H. pylori G27 (MOI = 100)." (PMID 23592983, 2013). "Infection of AGS cells evoked a rapid phosphorylation of Cav1 in AGS/Cav1 cells and of Src in both AGS/Cav1 and AGS/EV cells." (PMID 23592983, 2013). "Infection of AGS/Cav1 cells triggered the recruitment of p120 RhoGTPase-activating protein/deleted in liver cancer-1 (p120RhoGAP/DLC1) to Cav1 and counteracted CagA-induced cytoskeletal rearrangements." (PMID 23592983, 2013). "AGS/EV cells also produced more IL8 mRNA upon H. pylori G27 infection than AGS/Cav1 cells (64±19 EV versus 19±6 Cav1; *p = 0.0176; n = 3 per clone)." (PMID 23592983, 2013). "HAdV-D37 replicates readily in human corneal fibroblasts, and in our hands, knockdown of caveolin-1 reduced chemokine expression, suggesting that caveolin contributes to both productive infection and corneal inflammation." (PMID 24147000, 2013). "MDMs were also infected with AD8 or ADnefmut virus along with infection of Ad-Cav-1 or Ad-GFP to determine the level of ABCA-1 expression." (PMID 23067370, 2012). "In the current study, we clearly established that Cav-1 significantly reduces infection with virions produced from Cav-1 treated cells when compared to that of the same number of virions obtained from untreated cells." (PMID 23067370, 2012). "When caveolin-1 KO mice were infected with P. aeruginosa, increased bacterial colonization was observed compared to WT mice with higher mortality rates indicating that caveolin-1 is an important component in fighting infection." (PMID 21490807, 2011). "Here we provide evidence that during the early stages of infection, P+GC triggers a phosphotyrosine-dependent Cav1-Vav2-RhoA signaling cascade that elicits cytoskeletal rearrangements and effectively impedes bacterial uptake into host cells." (PMID 20808760, 2010). "During the early stages of infection, Neisseria gonorrhoeae triggers a phosphotyrosine-dependent Cav1-Vav2-RhoA signaling cascade that promotes the pathogen's extracellular state." (PMID 20808760, 2010). "Further we addressed the question if the infection of P. aeruginosa in DC also leads to differences in the Cav1 and SREBP protein levels." (PMID 19344509, 2009). "This caveolin-1 pathway was shown to be necessary for infection, as infection is blocked in cells where caveolin-1 protein levels were reduced using siRNA against caveolin-1." (PMID 19619315, 2009). "Their vacuoles/inclusions were demonstrated to acquire host cell caveolin-1 at entry and to accumulate it during later stages of infection." (PMID 15271223, 2004). "However, in contrast to the caveolin-1 results in the infection condition, LD4-PP increased the expression of RhoB both on the mRNA and protein level in E. coli-infected cells." (PMID 41415272, 2025).
infection (continued). "When we performed cell-to-cell spreading assays in Jeg3 cells simultaneously expressing GFP–flotillin-1 and mCherry–caveolin-1 in the receiving cells of the infection, we found that both flotillin-1 and caveolin-1 localized at the invaginations during these endocytic events." (PMID 40857412, 2025). "Modulating Cav-1 activity may also alter the immune response to enhance the host’s ability to clear infections." (PMID 39791703, 2024). "We further examined whether KSHV virions directly bind to CD109 and caveolin-1 during infection of senescent HuARLT cells." (PMID 39666389, 2024). "Moreover, in vivo, we observed that infection significantly reduced Cav-1 and BMPR2 expression and promoted significant pulmonary vascular injury and remodeling." (PMID 37908354, 2023). "Our study confirmed that IFITM proteins could directly influence the viral entry process by regulating the expression of endosomal compartments such as Rab5 and Caveolin-1 to inhibit viral replication or infection in HEK293 cells." (PMID 37112847, 2023). "Yet, we observed that infection with HAdV5 is caveolin-1-dependent and clathrin-independent." (PMID 35924932, 2022). "However, CAV-1 can possibly play some roles in infection with C. acnes or S. epidermidis since CAV-1 can be involved in the endocytosis pathway of some types of bacteria." (PMID 36532050, 2022). "Interestingly, the relative expression of ITGB1 in THP-1 and ITGB1/CAV-1 in HUVEC was significantly up-regulated after infection of L. interrogans." (PMID 36137081, 2022). "We have shown here that HAdV26 infection of human epithelial cells expressing low amount of αvβ3 integrin involves clathrin and is caveolin-1-independent, while HAdV26 infection of cells with high amount of αvβ3 integrin does not involve clathrin but is caveolin-1-dependent." (PMID 35924932, 2022). "Results of the co-localization experiment in the current study at different time intervals suggested that there was co-localization of EMCV-VP1 and caveolin-1 at 120 min post infection which implies that that caveolin-1 is required for early stage of EMCV replication." (PMID 33761945, 2021). "In order to explore whether EMCV exploits caveolin-1 during its infection, the expression of caveolin-1 during EMCV infection was investigated." (PMID 33761945, 2021). "Importantly, Src phosphorylation and CXCL1 expression were both reduced in HAdV-D37 infection of corneas in caveolin-1 knockout mice, relative to wild-type mice." (PMID 34960773, 2021). "In other words, CAV-1 plays a role in limiting IVA infection." (PMID 32357558, 2020). "One study pointed out that CAV-1 is essential for the interaction between M and HN, and reducing this interaction could affect the infection efficiency of PIV5." (PMID 32357558, 2020). "Besides, CAV-1 antagonists or inhibitors can be designed to block infections of PIV5, NDV, or used to cure diseases that are associated with elevated CAV-1." (PMID 32357558, 2020). "Except for Tat, Nef protein also has an interaction with CAV-1 during infection." (PMID 32357558, 2020). "Thereby, upregulated CAV1 level might contribute to the suppression of inflammation at later phase of infection." (PMID 28593998, 2017). "In addition to the tetraspanins we have found the membrane-associated levels of CD98, CD44, caveolin-1 and δ-catenin to be downmodulated upon HCMV-infection." (PMID 29121670, 2017). "Cav-2−/− mice could be used to better understand the effect of Cav-1 and Cav-2 on pathogen infection." (PMID 29250058, 2017). "Although there is an overall induction of inflammatory molecules during HIV infection, Cav-1 may be involved in the regulation of cytokine storms seen after infection." (PMID 28587148, 2017). "It is unclear whether CAV-1 detected by PCR in the organs of carrier foxes is viable and capable of lytic infections in permissible cell lines; this could be investigated using freshly harvested tissues." (PMID 27796367, 2016).
infection (continued). "CAV-1 was detected in the urine of three red foxes with inapparent infections." (PMID 27796367, 2016). "Considering that NS3 and NS2B colocalized with Cav-1 over the 36-h infection and that they were consistently present in DRMs, we hypothesized that the processing of DENV proteins is associated with caveolar lipid rafts." (PMID 24643062, 2014). "Western blot analysis of wild type and caveolin-1-/- mice corneas after infection revealed increased pSrc in wild type corneas at 1 and 24 hr post infection, compared to caveolin-1 -/- mice, suggesting that caveolin-1 is necessary for Src activation after infection." (PMID 24147000, 2013). "We sought to determine whether the increase in mortality was a result of increased incidence of viral entry due to Cav-1 knockdown, or reduced ability of morphant embryos to clear the infection." (PMID 23874753, 2013). "However, HAdV-D37 infection of corneal cells after caveolin-1 knock down by siRNA reduced IL-8 expression by ~ 50% (p=.0001)." (PMID 24147000, 2013). "Activation of PI3K also depended on the presence of Cav1 since Akt phosphorylation was detected in AGS-Cav1 upon N927 infection, but not in AGS cells deficient in Cav-1 expression." (PMID 23717204, 2013). "HAdV-D37 DNA was identified in caveolin-1 rich endosomal fractions after infection." (PMID 24147000, 2013). "The recent finding that ESCRT complex recruits caveolin-1 into maturing intralumenal vesicles may explain why E-1 and caveolin-1 are found in similar structures early in infection." (PMID 23227048, 2012). "However, the regulation of Cav1 by phosphorylation is poorly understood in the field of the pathogen infection." (PMID 22316086, 2012). "Moreover, in aged mice, caveolin-1 was found to be highly expressed in Peyer’s patch and spleen, which are targets for infection by Salmonellae." (PMID 20096033, 2010). "As shown, HVP16 infection was slightly increased in caveolin-1-depleted cells." (PMID 18836553, 2008). "We began by looking at infections in caveolin-1 positive HeLa cells." (PMID 15271223, 2004). "Additionally, genes related to cell adhesion such as ADGRF5, CAVIN2, FAT3, FILIP1, GSN, and TSPAN11 were downregulated in both the variants at 24hpi whereas CAV1, CAVIN1, GPC3, POSTN, SUSD2, and TSPAN7 were downregulated only after Delta variant infection at 24 hpi." (PMID 41200555, 2025). "Thus, we hypothesized that caveolin-1 could be limiting factor in αvβ3 integrin-mediated HAdV26 cell infection." (PMID 35924932, 2022). "The protein transporter caveolin 1 (Cav1) gene, which is highly expressed in lung microvascular endothelial cells as well as alveolar type I epithelial cells was also depressed in WT, but increased almost 2-fold between 7 and 14 days after infection in B2−/− lungs." (PMID 28779131, 2017). "We speculated therefore that Cav1 could play an important role during P+GC infection." (PMID 20808760, 2010). "After infection, Mfsd2a, MMP2 and MMP9 showed significantly up-regulation (P<0.05), while CAV-1 expression was significantly down-regulated (P<0.05), indicating that vesicle transport efficiency or barrier permeability was affected." (PMID 40642060, 2025). "Concurrently, the expression of the phosphorylated forms of Src (pSrc), Ezrin (pEzrin), and Cav-1 (pCav-1) is significantly upregulated at 15 and 30 min post-EMCV infection, reaching a peak at 15 min." (PMID 40631914, 2025). "To confirm the role of CD109 in mediating binding of KSHV virions to the cell surface during infection, we established stable CD109 and caveolin-1 cell lines in 293T cells." (PMID 39666389, 2024).